ZNF675 (zinc finger protein 675)
Description:
May be involved in transcriptional regulation. May play a role during osteoclast differentiation by modulating TRAF6 signaling activity.
Synonyms: TIZ; TBZF
Tractability: PROTAC: ubiquitination databases record sites on it.
Gene: Protein-coding gene on chromosome 19 (23,525,631 to 23,687,220, reverse strand). Ensembl gene ENSG00000197372.
Subcellular location: Nucleus
Pathways (Reactome):
Gene expression (Transcription): Generic Transcription Pathway
Gene Ontology:
Molecular function: protein binding; ubiquitin protein ligase binding; DNA binding; DNA-binding transcription factor activity, RNA polymerase II-specific; RNA polymerase II cis-regulatory region sequence-specific DNA binding; zinc ion binding
Biological process: negative regulation of canonical NF-kappaB signal transduction; negative regulation of cytokine-mediated signaling pathway; negative regulation of interleukin-1-mediated signaling pathway; negative regulation of JNK cascade; negative regulation of osteoclast differentiation; negative regulation of transcription by RNA polymerase II; negative regulation of tumor necrosis factor-mediated signaling pathway; bone resorption; regulation of DNA-templated transcription
Cellular component: nucleus; perinuclear region of cytoplasm
Genetic constraint (gnomAD): Loss-of-function variants: 35 observed, 54.45 expected, observed/expected ratio (o/e) 0.64, 90% interval 0.49 to 0.85. The upper end of that interval is the gene's LOEUF score, 0.85, which puts it in group 3 of 6, group 1 being the genes least tolerant of losing a copy. Missense variants: 654 observed, 659.88 expected, observed/expected ratio (o/e) 0.99, 90% interval 0.93 to 1.06. Synonymous variants: 198 observed, 216.53 expected, observed/expected ratio (o/e) 0.91, 90% interval 0.81 to 1.03.
Homologues: Orthologues: chimpanzee ZNF675 (99% identical). Paralogues in human: ZNF737 (68% identical), ZNF92 (67% identical), ZNF98 (65% identical), ZNF66 (65% identical), ZNF257 (64% identical), ZNF431 (64% identical), ZNF723 (64% identical), ZNF430 (63% identical), ZNF626 (62% identical), ZNF680 (62% identical), ZNF730 (62% identical), ZNF273 (62% identical), and 6 more.